PCNA (proliferating cell nuclear antigen)
Diseases named in the same sentence as PCNA in open-access papers (continued):
Sharing a sentence is not in itself a finding about the gene and the disease.
tumor (continued). "Inhibition of miR-191 increase PLCD1, and then decrease β-catenin, MMP-9, C-myc, N-cadherin, CDK4 and PCNA, ultimately leading to the decrease of proliferation, migration and invasion of OSCC cells, thus exerting anti-tumor effects." (PMID 37460940, 2023). "The IHC results of xenografted tumor showed that USP33 depletion inhibited the expression of Ki67, PCNA, TGFBR2 and ZEB1." (PMID 37322017, 2023). "The five remaining articles focused on the Epstein–Barr virus (EBV), proliferating cell nuclear antigen (PCNA), carbonic anhydrase 9 (CAIX), tumor–stroma ratio, or tumor-infiltrating lymphocytes." (PMID 37894447, 2023). "Although tumors formed by MMTV-neu:FAAH−/− showed a delayed tumor onset, they significantly increased their tumor growth rate compared to their FAAH+/+ counterparts, which was accompanied by increased levels of PCNA expression." (PMID 37253733, 2023). "Additionally, in an 4NQO-induced OSCC in situ mouse model, PFC@O2 significantly inhibited the tumor number and size as well as weakening the expression of the proliferative marker PCNA, which may be related to the improvement of hypoxia and downregulation of HIF-1α expression by PFC@O2." (PMID 36675491, 2023). "There was no expression of molecular indicators representing malignant behaviours, e.g., PCNA, CD44v6, and MMP-9 in HIFU-treated tumours compared to the control group." (PMID 37568958, 2023). "We biopsied tumor specimens from five patients with PR and PD to detect the protein and mRNA levels of RB1, CDKN2B, PCNA, and MCM7." (PMID 37781033, 2023). "Meanwhile, the expression of PCNA, VEGF, MMP‐2 and MMP‐9 was dramatically reduced in tumour‐bearing mice treated with PA in comparison with the vehicle group." (PMID 37038620, 2023). "GA administration also inhibited the tumor growth in xenografts in a dose-dependent manner by downregulating PCNA and CD31 levels and thereby inducing apoptosis in the tumor cell lines." (PMID 37049544, 2023). "We found that in MAGEA4+ tumor cells of SCCIS, the stem cell marker COL17A1 and the proliferation marker PCNA were significantly increased compared with the adjacent tissues." (PMID 38099574, 2023). "Expression of tumor biomarkers, such as PCNA and FASN, was also suppressed by CAPE and CAPPE in tumor tissue." (PMID 36765950, 2023). "Both Ki-67 and PCNA were significantly decreased in iberverin-treated Huh7.5.1 xenograft tumors, whereas cleaved Caspase-3 was remarkably increased, suggesting that iberverin could inhibit tumor growth of HCC by suppressing cell proliferation and promoting cell apoptosis in vivo." (PMID 38152688, 2023). "The xenograft tumor model indicated that FDX1 OE significantly inhibited the growth of UCEC and attenuated the PCNA, HK2, PKM2, and Ki-67 expression." (PMID 37945610, 2023). "In view of the high correlation between CHAF1A and PCNA protein expression in EC tumor tissues, we next analyzed the effect of CHAF1A and PCNA protein co-expression on patient prognosis." (PMID 37189802, 2023). "Here we also tested PCNA and P21 levels, and found that MCM4 silence inhibited its protein levels in tumour tissues." (PMID 37817427, 2023). "PCNA expression in the nuclei of tumor cells showed strong staining in the tumor cells of the DMSO-treated control group, whereas PCNA expression in the tumor cells of the GANT61-treated group was more sparse." (PMID 37240209, 2023). "Next, PCNA and MMP-2 expression was down-regulated following HSPB6 overexpression, suggesting the reduced ability of the tumor for migration and proliferation." (PMID 37861934, 2023).
tumor (continued). "Histologic analysis indicated that tumor samples derived from Ago-miR-497 treatment had a significantly decreased QKI expression than Ago-miR-NC tumors, similarly the proliferation marker PCNA was also inhibited." (PMID 37171386, 2023). "Subsequently, immunohistochemical analysis of the tumor was performed to detect FARSB and proliferating cell nuclear antigen (PCNA)." (PMID 38069034, 2023). "Thus, decreased protein expression of PCNA and Ki-67 might inhibit tumor cell proliferation." (PMID 36626251, 2023). "We found the expression level of PCNA and p-STAT3 was decrease greatly in MDG group (p < 0.05 and p < 0.05) compared with MD group, indicating the inhibition of tumor proliferation and NF-κB/IL-6/STAT3 signaling downstream protein." (PMID 37818040, 2023). "Considering its potential utility as an indicator for malignancies of SCCIS tumor cells, we performed IF co-localization of COL17A1, PCNA, and MAGEA4 in SCCIS tissues to investigate stemness and proliferative state of tumor cells." (PMID 38099574, 2023). "While sgCtrl mice developed full-blown tumors, mice expressing sgGpt1 showed smaller tumor nodules with reduced GPT1 expression, as well as reduced PCNA and S6 phosphorylation despite Δ90-β-catenin expression." (PMID 36256480, 2022). "The protein expression of RAB26, Ki67, PCNA as well as MMP2 and MMP7 in xenograft tumor tissues from each group was also determined by western blot assay." (PMID 35291909, 2022). "Our results showed that RAB26 silence reduced the expression of Ki67, PCNA, MMP2 and MMP7 in xenograft tumor samples, suggesting the suppression of RAB26 silence on NSCLC growth and metastasis in vivo." (PMID 35291909, 2022). "The tumor tissues examined the impacts of circTRIM28 knockdown and tamoxifen treatment on circTRIM28, miR-409-3p, HMGA2, PCNA, Cleaved-caspase 3, and MMP9 expression." (PMID 36180890, 2022). "Thinking on the same line, in this study, we found that our designed PCNA-targeting peptide, R11-NLS-pep8, has increased the efficacy of therapeutic drugs for lung cancer treatment by the synergistic killing of tumor cells." (PMID 36430528, 2022). "Western blot was applied to measure the mitigation of Mcl-1, PCNA, MMP-2, MMP-9, biomarkers of EMT process and the activation of caspase cascade, reflecting the influence of ID09 to tumor malignant biological behaviors in vivo." (PMID 35002504, 2022). "Next, we performed hematoxylin and eosin (H&E) staining and immunohistochemistry staining on the xenograft tumor sections with HPV16 E7, Caspase-3, CD31, and PCNA antibodies." (PMID 34349239, 2022). "The expression levels of proteins associated with the cell cycle (CDK4, CDK6 and cyclin D1), proliferation (Ki67 and PCNA) and the pathway (GSK-3β, p-GSK-3β, β-catenin) in tumor tissue samples were determined using western blotting." (PMID 34719320, 2022). "Genes associated with proliferation such as proliferating cell nuclear antigen (PCNA), prominin 1 (PROM1), HOP homeobox (HOPX), and olfactomedin 4 (OLFM4) were also upregulated in LPS treated IBD intestinal organoids and tumor enteroids." (PMID 35884586, 2022). "Silencing ALKBH5 as a demethylated enzyme of m6A was reported to reduce the tumor behavior of CRC cells and inhibited the expression of proliferating cell nuclear antigen (PCNA) and the migration induced by NEAT1." (PMID 35676702, 2022). "In contrast, tumour cell proliferation measured with PCNA and cyclin D1 was significantly reduced in GKO tumours compared with WT tumours in vivo." (PMID 35867177, 2022).
tumor (continued). "To explore the relationship between KSR2 and tumor cell proliferation, we examined co-expression of KSR2 and the proliferating cell nuclear antigen (PCNA), human Ki67 (MKI67) protein, and histone deacetylase 1 (HDAC1)." (PMID 35468812, 2022). "Meanwhile, the decreased tumor volume, weight, and protein expression of Ki67, VEGF, and PCNA as well as the increased extent of tumor cellular necrosis and damage were observed in RCC mice after treating with middle or high dose of RAC extract." (PMID 35942173, 2022). "After DCA treatment, the expression of PCNA-positive cells in the SF8628 tumors remained higher than in the PBT24 tumors of the respective groups, except in the tumor treated with the 5 mM MgDCA dose." (PMID 36142368, 2022). "We analyzed the ki-67, PCNA, and MCM in the tumor, which represent the proliferation and invasion of tumor cells by immunohistochemistry." (PMID 35874635, 2022). "In agreement with the increased tumor burden in NEMOLPC-KO p62ΔEx2-5 mice, the protein expression of the generic cell proliferation marker PCNA was 2.5-fold higher in these mice compared to NEMOLPC-KO mice." (PMID 35626041, 2022). "In contrast, the mice injected cells treated with miR-106b-5p had more considerable tumor burden than controls and displayed higher expression for Ki67, PCNA, Bcl-xL, and cyclin E1, along with a lower expression for BTG3 in tumor tissues relative to controls." (PMID 35342408, 2022). "The upregulation of the ORC family, RFC family, and PCNA in patients with GNAS copy number gain likely led to the elevated DNA biosynthesis and the enhanced tumor cell proliferation." (PMID 36307579, 2022). "Compared with the Ctrl or Ctrl+Sh-NC group, tumor tissues derived from the HG or HG + Sh-NC group exhibited increased positivity for Pin1, BRD4, NAP1L1, PCNA, and MMP9, and reduced positivity for P21." (PMID 35461311, 2022). "A previous report demonstrated that modification of proliferating cell nuclear antigen (PCNA) induces apoptosis and inhibits tumor growth through the linear ubiquitin chain." (PMID 35874839, 2022). "Protein levels of MS4A10, MS4A8, MS4A7, PCNA, BAX, Bcl-2, Caspase-3, and cleaved Caspase-3 were measured in tumor tissues." (PMID 36438804, 2022). "Next, we carried out the immunostaining for PCNA, an endogenous cell proliferation marker, to assess the growth inhibitory ability of DHS and RSV in LLC-tumours in vivo)." (PMID 35892684, 2022). "For example, lncSNHG5 works as a ceRNA by binding with miR-26a-5p, miR-132-3p or miR-154-5p to increase PCNA, GSK3β and CREB5 expression to drive cell proliferation, migration and metastasis of tumor cells 39-41." (PMID 36438499, 2022). "Therefore, a plethora of peptides mimicking the APIM or a sequence of caPCNA (“cancer-associated PCNA”), targeting the PIP-box or caPCNA were generated that selectively inhibit tumor cell growth, induce apoptosis, and enhance cytotoxicity of chemotherapy drugs on tumor cells." (PMID 36430528, 2022). "In mice injected with NCAPG knockdown cells, the tumours weighed less and the expression levels of NCAPG, PCNA, and Ki-67 were lower than those in the corresponding control mice." (PMID 35864529, 2022). "Proliferating cell nuclear antigen (PCNA), as an indicator of cell proliferation status, exists only in normal proliferating cells and tumor cells, and is closely related to cellular deoxyribonucleic acid (DNA) synthesis." (PMID 35692296, 2022). "Analyses of the biomarkers post-treatment with 131I-5-IPN revealed the reduced expression of proliferating cell nuclear antigen (PCNA) and Ki67 as well as the cell cycle blockage in the G2/M phase in tumor tissues." (PMID 36076924, 2022). "These associations were also maintained at the protein level across tumor types; expression of proteins that most highly correlated with repstress score included CYCLINB1, CYCLINE1, CHK2, 4EBP1, phosphorylated CDK1 and PCNA." (PMID 36381660, 2022).
tumor (continued). "Western blot results of tumor tissues demonstrated that knockdown PSMA1 inhibited the expression of C-Myc, PCNA, Ki67, YAP, and TAZ, which was consistent with the results in vitro." (PMID 36424389, 2022). "Here, we show that both Huh7-derived exosomes and overexpressed miR-4800-3p obviously increased PCNA expression and finally promoted HCC cell proliferation and tumor growth." (PMID 35756606, 2022). "A comparable PCNA staining pattern among MAPHDVI, HCC-MAPEpo, and ICC-MAPEpo tumors was observed, suggesting a similar proliferation in these tumor cells." (PMID 36494846, 2022). "Our analysis found marked increase in PCNA, Survivin and VEGF transcripts in SIRT3 overexpressing tumor tissues." (PMID 33937086, 2021). "Compared with si-ADAMTS9-AS1 + DMSO group, the expression levels of Ki67, PCNA, MMP-2 and MMP-9 in si-ADAMTS9-AS1 + INCB018424 group were prominently constrained, indicating decreased tumor proliferative activity (p < 0.05)." (PMID 34900984, 2021). "Toona sinensis crude extract decreased the incidences of SCCs, tumor number, tumor volume, and tumor burden in male Syrian golden hamsters by downregulating protein levels of survivin, XIAP, PCNA, iNOS, and COX-2." (PMID 34354591, 2021). "The markers synaptophysin, PCNA, DAXX, laminin and CD14 had similar expression levels in tumour and non-tumour tissue." (PMID 33906633, 2021). "H & E and PCNA staining of tumor tissues revealed that all monotherapy groups including GM101, SBHA, or MS-275 induced necrosis and inhibited proliferation of tumor cells compared to the PBS group." (PMID 34831034, 2021). "miR-1258 played an inhibitory role in the progression of GBM and functioned as a tumor suppressor by down-regulating E2F1 expression and attenuated E2F1-mediated downstream gene PCNA and MMP2 transcriptions." (PMID 34079762, 2021). "The tumor tissues in HFD-fed CXCR2 cKO mice had lower inflammatory areas and PCNA and F4/80 expressions, compared to those in HFD-fed WT mice, indicating a reduced tumor burden." (PMID 34638514, 2021). "The percentage of tumor cells with nuclear IRS-4 was 69.9 ± 3.2%, followed by nuclear PCNA 52.1 ± 7.8%, nuclear Ki-67 6.1 ± 1.1%, and finally pH3 with only 1.3 ± 0.2%." (PMID 34071030, 2021). "For example, the smaller cell cluster B4b was a highly proliferative tumor with cells at either the G2/M, or S phase and displayed high expression of MKI67, CDK4, and other proliferative markers such as PCNA, TK1, and TYMS." (PMID 34001881, 2021). "The expression of PCNA in the INT and IT groups were detected in the nucleus of tumor cells (respectively), while the expression of ErbB2 in both groups was found on the cell membranes (respectively)." (PMID 34164110, 2021). "Consistent with the in vitro data, the Ki67 and PCNA levels in tumor tissues were markedly decreased, indicating ZY0511 treatment inhibited the growth of tumor cells in vivo." (PMID 34491469, 2021). "Significant decreases in PCNA, Survivin and VEGF transcripts were observed in SIRT3 knockdown tumor tissues." (PMID 33937086, 2021). "The tumor growth was suppressed after depletion of HCG11, followed by suppressing Ki67, PCNA and Vimentin expression, increasing TUNEL-positive cells and E-cadherin expression." (PMID 34230221, 2021). "In accordance with tumor staining results, we observed increased levels of IRF9 and VCAN in IRF9-overexpressing tumors; PCNA staining also showed an increase in PCNA expression in these tumors." (PMID 33430083, 2021). "To test a possible synergism of PCNA and γ-tubulin in the maintenance of indefinite proliferation and development of cancer, we evaluated a potential interrelationship between PCNA and TUBG1 in different tumor types." (PMID 34158617, 2021). "Quantification of the distribution of the staining for TNT-associated proteins, 14-3-3γ and GAP43, as well as PCNA and GFAP, indicates the exquisite distribution of all these components at the tumor-tissue interface." (PMID 34267246, 2021).
tumor (continued). "The 5 mM MgDCA impact was more potent and had similar effects on U87 MG and PBT24 tumors, and its impact was also reflected in changes in PCNA and EZH2 expression in tumor cells." (PMID 33716589, 2021). "One study explored distal-less homeobox 6 antisense 1 as an oncogene in OC and found that it accelerated tumor progression by upregulating four-and-a-half LIM domains protein 2 and PCNA via miR-195-5p." (PMID 34721621, 2021). "To test whether the observed up-regulation of DNMT1 expression in ALK tumor samples is associated with deregulation of cell cycle–associated genes, we performed Western blot analysis using antibodies against c-MYC, CDK4/CDK6, cyclin D1, and the proliferation marker PCNA." (PMID 33310759, 2021). "Our studies illustrated that miR-1258 functioned as a tumor suppressor in GBM by directly targeting E2F1, subsequently inhibiting PCNA and MMP2 transcriptions, which contributed to new potential targets for GBM therapy and other E2F1-driven cancers." (PMID 34079762, 2021). "Compared with the LY group, the expression of PCNA, CD34 and PATK in the transplanted tumor tissues of the P + LY group was down-regulated, and the difference was statistically significant (F = 0.000)." (PMID 34323647, 2021). "Western blot result exhibited that compared with si-NC + DMSO group, the expression levels of Ki67, PCNA, MMP-2 and MMP-9 in si-ADAMTS9-AS1 + DMSO group were markedly boosted, indicating increased tumor proliferative activity." (PMID 34900984, 2021). "Compared with the IGF group, the expressions of PCNA, CD34 and PATK in transplanted tumor tissues in the P + IGF group were down-regulated, and the difference was statistically significant (P = 0.000)." (PMID 34323647, 2021). "The expression of SETD8 and PCNA are correlated in cancer samples, implying the crucial role of SETD8-mediated methylation of PCNA in tumor development." (PMID 34671219, 2021). "The downregulation of IRF9 and VCAN expression was conserved until tumor excision, STAT1, and CDKN1A expression showed decreased tendency and STAT2, and PCNA expression were significantly reduced in the IRF9-knockdown group." (PMID 33430083, 2021). "Similar results were noticed at the protein level for PCNA, Survivin and VEGF in SIRT3 knockdown tumor tissues." (PMID 33937086, 2021). "By contrast, the NK-exosome-treated tumor group exhibited a significant reduction in Bmi-1, MMP-3, IL-1β, IL-6, TNF-α, Bax, Bcl-xL, and PCNA expression compared with that in the tumor group." (PMID 34527741, 2021). "We also analyzed the levels of PCNA, Survivin and VEGF transcripts and protein in SIRT3 overexpressing (Hs294T-SIRT3-Flag) tumor tissues." (PMID 33937086, 2021). "Subsequently, we performed the mRNA and protein detection of proliferation markers (CYCLIN B1, PCNA, and KI-67) and apoptosis markers (BAX and BCL2) in the tumor tissues of each mice group." (PMID 34447747, 2021). "Western blot and qPCR results about the levels of PCNA, E-cadherin, N-cadherin, VEGF, TGF-β in each xenograft tumor were also consistent with the result of IHC." (PMID 34093546, 2021). "Firstly, we observed decrease in both tumor volume and tumor weight with CARMN overexpressed cells compared with control cells, with lower level of Ki67/PCNA positive rate and higher level of TUNEL positive rate." (PMID 34162418, 2021). "We evaluated the gene expression of miR-525-5p, ARF6, PCNA and CDK2 in the xenograft tumor tissues by RT-qPCR." (PMID 34621682, 2021). "Western blot result uncovered that Ki67, PCNA, MMP-2, and MMP-9 were notably repressed upon ADAMTS9-AS1 overexpression (p < 0.05), indicating that the tumor proliferation was decreased." (PMID 34900984, 2021). "The elevated expression level of Ki67 and PCNA in oe-ZNF750 and diminished level in sh-ZNF750 groups was in consistent with the observation results from the tumor growth in vivo." (PMID 35003347, 2021).